IL15RA (interleukin 15 receptor subunit alpha)
Diseases named in the same sentence as IL15RA in open-access papers (continued):
Sharing a sentence is not in itself a finding about the gene and the disease.
psoriasis (5 papers, 2017 to 2026). An autoimmune condition characterized by red, well-delineated plaques with silvery scales that are usually on the extensor surfaces and scalp. "Using unique mouse models of psoriasis relapse, we found that high humidity exposure exacerbated psoriasis recurrence by increasing skin-resident memory CD8+ T (TRM) cells through a mechanism depending on its upregulation of IL-15Rα on keratinocytes." (PMID 41990265, 2026). "First positive proof–of–concept for the clinical effects of topical cefazolin, first–generation cephalosporin which was identified as a small molecule IL–15Rα inhibitor and used in the treatment of psoriasis confirms this approach." (PMID 36903533, 2023). "Thus, our findings enhanced a new understanding of how climatic factors govern psoriasis recurrence and unveiled a role for IL-15Rα-expressing keratinocytes in skin CD8+ TRM formation and psoriasis relapse." (PMID 41990265, 2026). "Indeed, we demonstrated before that endogenous soluble IL-15Rα derived from epidermal stroma, protects against dendritic cell/IL-15-mediated, T cell-driven skin inflammation in vivo, and is relevant to human psoriasis." (PMID 31996218, 2020).
Anxiety (4 papers, 2011 to 2021). Intense feelings of nervousness, tension, or panic often arise in response to interpersonal stresses. "These identified abnormalities in transcription factors indicated an association with numerous mental health disorders in IL15Rα KO mice, including less anxiety or the memory disorders." (PMID 33613171, 2020). "Specifically, IL-15 crosses the blood–brain barrier and modulation of IL-15/IL-15rα impacts sleep patterns, anxiety behavior pathways, and anti-depression pathways, which collectively has profound global impacts." (PMID 34326778, 2021). "In a former anxiety evaluation trial, IL15Rα KO mice showed reduced anxiety both in the open field test and elevated plus maze test." (PMID 33613171, 2020). "In this study, the expression of Arc was found to decrease in IL15Rα KO mice, supporting the behavior with less anxiety." (PMID 33613171, 2020). "IL-15Rα KO mice show hyperactivity, depressive-like behavior, reduced anxiety, and impaired memory." (PMID 33613171, 2020). "Animals lacking IL15RA show depressive-like behavior and impaired memory, even though they show reduced anxiety." (PMID 26441851, 2015). "Furthermore, the lack of Il15ra resulted in reduced anxiety in these mice, which indicates a comparable behavioral phenotype as observed in the present study." (PMID 21857948, 2011).
COVID-19 (4 papers, 2021 to 2025). A disease caused by infection with severe acute respiratory syndrome coronavirus 2. "Interestingly, elevated levels of three proteins, namely SLAMF1, IL18 and IL15RA were associated with the risk of developing critical COVID-19 and Long COVID." (PMID 40475767, 2025). "After adjustment for confounding factors, seven proteins that were highly abundant and associated with an increased hazard of critical COVID-19 outcome were SLAMF1, CCL25, IL2RB, IL10RA, IL15RA, IL18 and CST5." (PMID 40475767, 2025). "Protein levels of SLAMF1, IL15RA, and IL18 associated with critical illness during the acute phase of COVID-19 also predicted Long COVID risk." (PMID 40475767, 2025). "Here, we demonstrated that the unique signature featuring SLAMF1, CCL25, IL2-RB, IL10RA, IL15RA, IL18, and CST significantly increased the risk of critical illness in COVID-19 patients." (PMID 40475767, 2025). "Notably, baseline protein levels of SLAMF1, IL15RA and IL18 associated with the critical illness during the acute phase of COVID-19 were also able to predict Long COVID risk." (PMID 40475767, 2025). "Thrombocytopenia, which was more pronounced in MIS-C and correlated significantly with IL15 and IL15/IL15RA composite transcript score in both KD and MIS-C, has also been reported in COVID-19 and postulated because of various mechanisms." (PMID 35577777, 2022). "We now show that the same ViP signatures can objectively demonstrate the shared immunophenotypes between all three syndromes (COVID-19, KD and MIS-C), which features an upregulation of the IL15/IL15RA pathway." (PMID 35577777, 2022). "When comparing COVID-19 mild vs critical patients, we identified IFNLR1, IFNA1, CXCL9, CXCL10, IL15 and IL15RA to be upregulated in mild patients." (PMID 33473155, 2021). "Additionally, the predictive power assessed by the AUC curve showed that IL15RA (AUC=0.842), SLAMF1 (AUC=0.775) and IL18 (AUC=0.775) as the top three proteins predicting critical COVID-19 illness." (PMID 40475767, 2025). "Levels of SLAMF1, CCL25, IL2RB, IL10RA, IL15RA, IL18 and CST5 were significantly upregulated in patients with critical COVID-19 illness compared to individuals negative for COVID-19." (PMID 40475767, 2025).
leukemia (4 papers, 2016 to 2023). A malignant (clonal) hematologic disorder, involving hematopoietic stem cells and characterized by the presence of primitive or atypical myeloid or lymphoid cells in the bone marrow and the blood. "Moreover, 65% of NOD.scid mice develop spontaneous thymomas by 10 months of age, while 100% of NOD.scid mice lacking IL-15 or IL-15Rα develop spontaneous lymphoma/leukemia by 8 months of age." (PMID 36765626, 2023). "Moreover, 4G-CAR–transduced C1498 leukemia cells (which do not express IL-15-Rα) secreted high levels of mIL-15." (PMID 33156338, 2021).
Arthritis (3 papers, 2022 to 2024). Inflammation of a joint. "The decreased levels of IL-15Rα in individuals progressing to arthritis are, in contrast, significantly different from levels in healthy controls." (PMID 38457608, 2024). "Overall, our results demonstrated that selectively avoiding IL-15 signaling through the trimeric IL-15Rα/IL-2Rβ/γc receptor is important for reducing inflammation in the collagen-induced arthritis model." (PMID 35592318, 2022). "Notably, a mutant IL-15 construct with impaired ability to bind IL-2Rβ (NANTIL-15) selectively blocked IL-15 signaling via the trimeric IL-15Rα/IL-2Rβ/γc receptor and reduced inflammation in a collagen-induced arthritis model, without inhibiting NK or CD8+ T cell homeostasis." (PMID 38919611, 2024).
autoimmune disease (3 papers, 2021 to 2022). A disorder resulting from loss of function or tissue destruction of an organ or multiple organs, arising from humoral or cellular immune responses of the individual to their own tissue constituents. "However, studies on the pathogenic role of IL-15 in inflammatory and autoimmune diseases indicate that IL-15 can signal independently of IL-15Rα via the IL-15Rβγc dimer." (PMID 34956227, 2021). "Intriguingly, numerous infectious and autoimmune diseases shared the IL15/IL15RA-centric cytokine response, which is in keeping with prior observations." (PMID 35577777, 2022). "As in various autoimmune diseases, IL-15/IL-15Rα complexes were found at high levels in B6/lpr-p2x7KO sera." (PMID 36248812, 2022). "A few studies including ours have also reported that IL-15 is more critical than IL-15Rα in the context of antiviral responses, autoimmune disease and antitumor immunity." (PMID 34956227, 2021).
depression (3 papers, 2021 to 2025). "The present study investigated potential connections between IL-15Rα levels in serum and the risk of schizophrenia and depression." (PMID 35356722, 2022). "In this study, we investigated whether IL-15Rα was associated with the risk for psychiatric disorders by comparing the serum-soluble IL-15Rα levels in patients with schizophrenia or depression and healthy controls." (PMID 35356722, 2022). "Due to the overlapping symptomology and pathogenesis observed for schizophrenia and depression, the present study attempted to determine whether IL-15Rα was associated with the risk of schizophrenia or depression." (PMID 35356722, 2022). "We have observed that IL-15Rα KO mice display defects in GABAergic and serotonergic transmission, contributing to the phenotypes of schizophrenia and depression." (PMID 35356722, 2022). "Collectively, these results indicate that IL-15Rα plays an important role in schizophrenia and depression." (PMID 35356722, 2022). "Our previous studies documented that interleukin-15 receptor α (IL-15Rα) knockout (KO) mice exhibited hyperactivity, memory impairment, and desperate behavior, which are core features of schizophrenia and depression." (PMID 35356722, 2022). "Third, most of the patients were taking antipsychotics (68% in schizophrenia and 72% in depression), so the influence of antipsychotics on IL-15Rα levels should be considered." (PMID 35356722, 2022). "The presence of inflammation is an essential etiological hypothesis in psychiatric diseases, including schizophrenia and depression, and we observed alterations in the serum levels of IL-15Rα in patients with schizophrenia and depression in this study." (PMID 35356722, 2022). "As the ligand of IL-15Rα, IL-15 is a cytokine especially poised to have a pivotal role in CNS organization, and it also has been reported to be a biomarker of schizophrenia and depression." (PMID 35356722, 2022).
gastric cancer (3 papers, 2017 to 2024). A primary or metastatic malignant neoplasm involving the stomach. "In this study, we constructed the IL-15Rα into the extracellular region of CAR structure, which enhanced the anti-tumor effects of CAR-T cells against gastric cancer compared with conventional CAR-T." (PMID 38368374, 2024). "CAR-T cells with an IL-15/IL-15Rα sushi domain displayed enhanced anti-tumor efficacy compared with conventional CAR-T, and GLIRP1 knockdown in gastric cancer further promoted the function of CAR-T cells." (PMID 38368374, 2024). "In this study, we constructed a new CAR structure with an IL-15/IL-15Rα sushi domain (CAR-ss-T) on the CAR extracellular region, which facilitate cytotoxicity against gastric cancer cells compared with conventional CAR." (PMID 38368374, 2024). "CAR-T cells constructed with IL-15/IL-15Rα (CAR-ss-T) showed significantly improved CAR-T cell expansion, cytokine production and cytotoxicity, and resulted in superior tumor control compared to conventional CAR-T cells in gastric cancer." (PMID 38368374, 2024). "Through a literature review, we found that in the absence of immune cells, IL-15RA on the surface of gastric cancer cells induces a malignant phenotype, including increased cell growth, migration and invasion and decreased apoptosis." (PMID 39396119, 2024). "Besides, after co-culture with gastric cancer cell HGC27, the percentage of total CD8+ T cells and CAR+ T cell in CD8+ T cells was not changed significantly in CAR-ss-T, suggesting the existence of IL-15/IL-15Rα did not affect the proportion of CD8+ and CD4+ T cells." (PMID 38368374, 2024).
lymphoma (3 papers, 2023). A malignant (clonal) proliferation of B- lymphocytes or T- lymphocytes which involves the lymph nodes, bone marrow and/or extranodal sites. "We, finally, challenged the anti-lymphoma activity of NK-92-CAR.19-IL-15/IL-15Rα cells in a Raji xenograft immunodeficient mouse model." (PMID 37818365, 2023). "Thus, CD19.CAR NK cells co-expressing IL15/IL15Rα exhibited superior antitumor activity against lymphoma cells in vivo compared to CAR construct co-expressing soluble IL-15 or no cytokines." (PMID 37818365, 2023).
sarcoidosis (3 papers, 2012 to 2022). Sarcoidosis is a multisystemic disorder of unknown cause characterized by the formation of immune granulomas in involved organs. "This analysis further supported the crucial relationships between T-bet, CCL5, IFNG, IL2RB, and IL15RA, together with let-7d and miR-202 in progressing sarcoidosis." (PMID 26696750, 2015). "The close relationships in sarcoidosis as a whole were found between T-bet and IL2RB, IL15RA, and CXCR3, which was related to CXCR6 and IFNG." (PMID 26696750, 2015). "In regressing sarcoidosis, relationships were observed between T-bet and IL2RB, IL15RA, CXCR3, IL2, and IFNG." (PMID 26696750, 2015). "Our correlation analysis revealed relationship of T-bet and sarcoid inflammation, namely, its association with key sarcoidosis-associated cytokine IFNG, and receptors IL2RB, IL15RA, CXCR3, and CXCR6, regardless of the disease outcome." (PMID 26696750, 2015). "In progressing sarcoidosis, T-bet related to CCL5, IL2RB, IL15RA, and IFNG." (PMID 26696750, 2015).
schizophrenia (3 papers, 2016 to 2022). A major psychotic disorder characterized by abnormalities in the perception or expression of reality. "The underlying reason for reduced soluble IL-15Rα in the plasma of schizophrenia patients was elusive." (PMID 35356722, 2022). "There is a significant association of hippocampal IL15Rα expression with schizophrenia (p = 8.32 × 10–5), with a significant FDR (p = 0.01046)." (PMID 33613171, 2020). "Although few reports have described a role for IL-15Rα in schizophrenia, several studies have demonstrated that the underlying mechanism might be related to abnormal lipid and energy biosynthesis and metabolism." (PMID 35356722, 2022). "Associations of the serum IL-15Rα levels and phenotypes in schizophrenia patients." (PMID 35356722, 2022). "Furthermore, we found a rare mutation in the IL-15RA gene that impeded IL-15Rα intracellular signal transduction in schizophrenia patients." (PMID 35356722, 2022). "We investigated the circulating levels of soluble IL-15Rα and analyzed potential links between the IL-15Rα levels and clinical symptoms present in schizophrenia or depressive patients." (PMID 35356722, 2022). "A significant decrease in serum IL-15Rα levels was present in schizophrenia patients compared with healthy controls (p = 0.049) or depressive patients (p = 0.043)." (PMID 35356722, 2022). "To explore the direct relationship of IL-15Rα with the schizophrenia-like phenotypes in schizophrenia, we established the IL-15Rα KO mice." (PMID 35356722, 2022). "We analyzed the association of IL-15Rα levels and clinical symptoms in the schizophrenia patients further to assess the relationship between IL-15Rα and schizophrenia phenotypes." (PMID 35356722, 2022). "The average serum IL-15Rα levels were 150.12 (SD = 99.57), 208.36 (SD = 101.72), and 195.13 (SD = 110.51) pg/ml in the schizophrenia patients, depressive patients, and healthy controls, respectively." (PMID 35356722, 2022). "The IL-15Rα KO mice displayed pronounced pre-pulse inhibition impairment, which was a typical symptom of schizophrenia." (PMID 35356722, 2022). "Schizophrenia patients seem to have higher IL15Rα expression levels in the hippocampus than controls." (PMID 33613171, 2020). "IL15Rα expression data from brains of both schizophrenia patients and healthy controls were extracted from the SZDB database." (PMID 33613171, 2020). "Several reasons might be related to the different expression of IL-15Rα in serum between schizophrenia patients and depressive patients." (PMID 35356722, 2022). "Considering the close relationship between impairment of brain development and schizophrenia, we speculated that a greater reduction in IL-15Rα might accompany schizophrenia." (PMID 35356722, 2022). "Notably, we also found a distinct decrease of IL-15Rα in schizophrenia patients compared to depressive patients." (PMID 35356722, 2022). "Therefore, although this was a pilot study, when the data were considered collectively, they revealed a definitive reduction in serum IL-15Rα levels in schizophrenia patients." (PMID 35356722, 2022). "The data from IL15Rα–/– mice led us to propose that sterol biosynthetic and metabolic in the brain may be a key factor in schizophrenia-like etiology." (PMID 33613171, 2020). "Moreover, a significant negative association was observed between the circulating IL-15Rα levels and excited phenotypes in the schizophrenia patients." (PMID 35356722, 2022). "We observed reduced serum IL-15Rα levels in schizophrenia patients, but not depressive patients compared with controls." (PMID 35356722, 2022). "We found that serum IL-15Rα levels showed a considerable, negative correlation with the excited phenotype in schizophrenia patients." (PMID 35356722, 2022). "For schizophrenia patients, a remarkable negative correlation existed between the levels of IL-15Rα and the excited component (B = −11.765, t = −2.603, p = 0.014)." (PMID 35356722, 2022).
schizophrenia (continued). "Furthermore, the IL-15Rα KO mice showed a significant decrease in PPI, which was consistent with our published data that showed reduced PPI in schizophrenia patients." (PMID 35356722, 2022). "Second, the confounding effect of antipsychotics on the changes in serum IL-15Rα levels in patients could not be ruled out although we did not observe any effect of antipsychotic treatment on serum IL-15Rα levels in schizophrenia patients." (PMID 35356722, 2022). "Moreover, there was no remarkable difference in IL-15Rα levels in schizophrenia patients treated with or without antipsychotics before enrollment." (PMID 35356722, 2022). "Interestingly, we found a significant reduction in IL-15Rα levels in schizophrenia but no changes in depressive patients." (PMID 35356722, 2022). "Furthermore, such insufficiency or lack of IL-15Rα could induce hyperexcitability in the experimental mouse model and schizophrenia patients." (PMID 35356722, 2022).
viral infection (3 papers, 2014 to 2025). "During virus infection this can be achieved via DC-presented IL-15/IL-15Rα, an interaction described as the regulatory synapse." (PMID 25412359, 2014).
acne (2 papers, 2024). An inflammatory process of the sebaceous glands which is characterized by comedones, nodules, papules and/or pustules on the skin. "Moreover, the function of the other genes, including FAS, SDC1, ANGPTL2, IL-15RA, INHBA, and OSMR in lymphocytes, keratinocytes, fibroblasts, and smooth muscle, are yet to be explored, suggesting that acne involves not only the skin’s surface but also a wider systemic dysregulation." (PMID 38854033, 2024).
B cell lymphoma (2 papers, 2017 to 2023). "The IL-15 superagonist/IL-15Rα-Fc fusion complex (designated ALT-803) has previously been shown to enhance NK lysis of tumor cells and to augment NK-cell ADCC of B cell lymphomas directed by rituximab." (PMID 29088859, 2017).
Burkitt lymphoma (2 papers, 2021 to 2024). A rare form of malignant mature B-cell non-Hodgkin lymphoma. "Another group used mRNA electroporation to engineer moDCs to produce IL-15/IL-15Rα or IFN-α leading to increased NK cell activation and cytotoxic activity against Burkitt lymphoma cells in vitro." (PMID 34054844, 2021). "Studies have shown that the combination of anti-CD20 or anti-CD79 antibodies with NKTR-255 (a polymer-conjugated, IL-15Rα-dependent, recombinant human IL-15 agonist) can significantly enhance the in vitro cytotoxicity of CD19-CAR-NK cells against Burkitt’s lymphoma (BL) cells." (PMID 39007146, 2024).
diabetes (2 papers, 2017 to 2024). "Similarly, we also identified many metabolites and several proteins (e.g., SLAMF1: signaling lymphocytic activation molecule and IL-15RA: interleukin-15 receptor subunit alpha) associated with HIV infection and diabetes in the same direction." (PMID 38643166, 2024).
Hantavirus Infection (2 papers, 2014 to 2019). "Corroborating this notion, in vitro, hantavirus infection was found to induce transcription of IL‐15 and IL‐15Rα mRNAs and cause increased IL‐15 and IL‐15Rα cell surface expression." (PMID 30663801, 2019).
Immunodeficiency (2 papers, 2020 to 2022). Failure of the immune system to protect the body adequately from infection, due to the absence or insufficiency of some component process or substance. "Several published reports have confirmed that IL-15Rα insufficiency results in multiple disorders, including but not limited to immunodeficiency, skeletal muscle variations, and a range of neurological symptoms." (PMID 35356722, 2022).